TNF (tumor necrosis factor)
Diseases named in the same sentence as TNF in open-access papers (continued):
Sharing a sentence is not in itself a finding about the gene and the disease.
depression (continued). "Prior evidence supports that the development of depression is related to the levels of proinflammatory cytokines TNF-α and to interleukin-6 (IL6, the 33rd) in the brain." (PMID 21494644, 2011). "In the further study, we followed the development both of pain intensity and depression scores parallel to the TNFα level in a longitudinal design of 6 months, and tried to determine the potential interaction between TNFα, pain and depression." (PMID 20937109, 2010). "A possible explanation for the decline of TNF-α serum levels is that patients with comorbid depression took significantly more NSAIDs at T0 (28%) than patients with cLBP alone (7%) and used these drugs significantly less at T3 (7%) than at T0." (PMID 20937108, 2010). "It seems that TNFα somehow acts as a mediator in both cLBP and depression, involving similar mechanisms that will be interesting to follow in further studies." (PMID 20937109, 2010). "Rather, it seems that TNFα somehow acts as a mediator in both cLBP and depression, by similar mechanisms." (PMID 20937109, 2010). "Concerning the immunological mechanisms, certain pro-inflammatory cytokines, mainly IL-6, IL-1β and TNFα, have been recently pointed out as pivotal molecules for depression-related behaviors following infection." (PMID 21194425, 2010). "The experimental evidence provided herein clearly suggests a link between the cytokine TNFα and the kinin B1 receptor upregulation in depression genesis." (PMID 21194425, 2010). "Of note, patients with major depressive disorder have increased expression of soluble TNFα receptors, and patients under treatment with TNFα antagonists display a general improvement of depressive symptoms and life quality." (PMID 21194425, 2010). "In this study we investigated the influence of depression on therapy outcomes such as TNF-α serum levels, pain intensity and back function in patients with cLBP." (PMID 20937108, 2010). "Treatment with TNF-alpha (Tumor Necrosis Factor alpha) has the frequent side effect of inducing depression and there have been reports of mania." (PMID 21092101, 2010). "Integrating these pieces of information our model shows how excessive alcohol use would be expected to lead to reduced TNF signaling, reduced MTHFR expression, and increased susceptibility to depression." (PMID 18822146, 2008). "The proinflammatory cytokines that researchers identified most consistently as being elevated in depression are interleukin-1β (IL-1β), interleukin-6 (IL-6), tumor necrosis factor-α (TNF-α), and more recently, interferon-γ (IFN-γ)." (PMID 17397549, 2007). "In a study of older adults, the combination of depression and higher omega-6: omega-3 ratios dramatically increased levels of proinflammatory cytokines (IL-6 & TNF-α) beyond the individual contribution of either variable alone." (PMID 17397549, 2007). "Moreover, MGO administration increased the levels of cytokines (IL-1β, IL-6, and TNF-α) in the serum, which led to neuropsychiatric disorders and depression as shown in behavior tests (i.e., OFT, TST, and FST)." (PMID 41355970, 2026). "Network pharmacology identified 156 intersecting targets between YHD and depression-related pathways, primarily involved in neuroactive ligand-receptor interactions, dopaminergic synapses, and inflammatory processes (e.g., TNF signaling and cytokine production)." (PMID 42006145, 2026). "At baseline, depression was significantly correlated with TNF-α, IL-6, and IL-1β." (PMID 41600880, 2026). "Both anti-TNF and non-anti-TNF biologics were associated with reduced risk of anxiety/depression compared with non-AT therapy (both HR 0.8; p < 0.001 and p = 0.004, respectively)." (PMID 41976865, 2026). "Additionally, autoimmune disease patients often report reduced depression as an “incidental benefit” after TNF inhibitor use." (PMID 41583906, 2026).
depression (continued). "Depression patients also present increased TNF, macrophage colony-stimulating factor (MCSF), and IL-12 in the intestinal mucosa and reduced abundances of Clostridium, Roseburia, Haemophilus, SMB53, and Turicibacter, which are positively correlated with propionate and butyrate levels." (PMID 40804450, 2025). "Results show that patients with depression had significantly higher increases at 2 years compared to baseline for all investigated parameters (CRP—p = 0.001/Fibrinogen—p < 0.001/Interleukin-6—p < 0.001/TNF-α -p < 0.001/Cortisol—p < 0.001)." (PMID 40363978, 2025). "Mounting evidence underscores the intricate interplay between depression and inflammation, with studies revealing elevated levels of inflammatory markers, such as tumor necrosis factor α (TNF-α) and nuclear factor kappa B subunit 1 (NF-κB1), in individuals with depression." (PMID 39851527, 2025). "Additionally, vitamin D modulates inflammatory markers such as IL-6 and TNF-α, both central to the systemic inflammation observed in depression." (PMID 40563330, 2025). "Inflammatory mediators, such as tumor necrosis factor-alpha (TNF-α) and interleukin-6 (IL-6), can reach brain tissue and influence the development of depression and sleep disorders by modulating synaptic transmission, neuronal excitability, neuronal survival, and synaptic plasticity." (PMID 40927014, 2025). "In addition, the oxidative stress that accompanies pain and depression activates glial cells, which release proinflammatory cytokines (TNF-α and IL-1β), chemokines, and neurotoxic substances such as NO in the central nervous system (CNS)." (PMID 40225229, 2025). "Individuals with depression exhibit distinct gut microbiota profiles, including reduced abundance of short-chain fatty acid (SCFA)-producing bacteria (e.g., Faecalibacterium and Roseburia) and elevated pro-inflammatory cytokines (e.g., IL-6, TNF-α), correlating with depression severity." (PMID 41573044, 2025). "Additionally, MAZ51 led to a decrease in the protein levels of PSD95 as well in the hippocampus, which was paralleled by an elevation in TNF-α and IL-6 levels, and aggravated depression-like behavior." (PMID 40809378, 2025). "Mood disorders, including depression, post-traumatic stress disorder (PTSD), and anxiety, are associated with low-grade chronic neuroinflammation, detectable through peripheral inflammatory markers such as TNF-α." (PMID 40143157, 2025). "Pro-inflammatory proteins, such as TNF-α, IL-1 and IL-6, are potent activators of the hypothalamic–pituitary–adrenal axis (HPA) and release of these proteins leads to hypersecretion of adrenal glucocorticoids which have been linked to depression." (PMID 39867847, 2025). "Individuals with depression were found to have elevated levels of proinflammatory cytokines, such as interleukin (IL)-6, IL-1β, tumor necrosis factor (TNF)-alpha, and C-reactive protein, in both their peripheral blood and cerebrospinal fluid, compared with healthy controls." (PMID 40283919, 2025). "Clinical evidence supports the involvement of TNF-α in depression." (PMID 40001206, 2025). "Notably, research shows that TNF-α-blocking drugs like etanercept can reduce both seizures and depression symptoms in animal studies, suggesting potential new treatment options." (PMID 40941042, 2025). "In an alcohol-LPS combination-induced mouse model, this bacterium reduced serum LPS and pro-inflammatory cytokine (TNF-α, IL-1β) levels and corrected expression abnormalities of depression-related genes, indicating potential for intervening in alcohol-related mood disorders." (PMID 41017972, 2025). "After the first step of adjustment (for age and gender), TNF-α and IL-6 levels were no longer significantly associated with depression." (PMID 39922907, 2025).
depression (continued). "Results show that patients with depression had significantly higher increases at 2 years compared to baseline for all investigated parameters (CRP—p = 0.032/Fibrinogen—p = 0.030/Interleukin-6—p < 0.001/TNF-α -p = 0.007/Cortisol—p < 0.001)." (PMID 40363978, 2025). "The significant decrease in TNF-α levels observed with HA and fluoxetine accentuates its potent anti-inflammatory properties, which support its effectiveness as a treatment alternative for depression." (PMID 40574754, 2025). "Obesity-induced inflammation significantly heightens oxidative stress by increasing adipokine secretion—such as IL-6, IL-1, and tumor necrosis factor-alpha—while simultaneously impairing insulin regulation, thus elevating risks for type 2 diabetes and depression." (PMID 40426956, 2025). "Brain TNF drives depression-like behavior and chronic pain in arthritis." (PMID 40759564, 2025). "Lep exhibited the ability to reduce serum LPS, IL-6, and TNF-α levels in stressed mice and repair the colonic mucosal injury, confirming that Lep can modulate systemic and neuro-inflammation, thereby alleviating the depression-like behavior." (PMID 39856996, 2025). "Additionally, moderate PA reduces systemic inflammation by lowering levels of pro-inflammatory cytokines, such as IL-6 and TNF, which are often elevated in individuals with depression." (PMID 40420074, 2025). "Study had proved that Ziyan Green Tea administration could stimulate the levels of 5-HT, BDNF, and DA in the brain, and reduce the inflammatory factors, IL-6 and TNF-α, to prevent depression induced by CUMS." (PMID 39861389, 2025). "Additionally, patients with major depression showed significantly elevated levels of proinflammatory cytokines (TNF-a, IL-2, IL-12) after sertraline use." (PMID 40283042, 2025). "TNFα is the most relevant for depression as it regulates extracellular serotonin levels." (PMID 40352929, 2025). "More direct evidence of the relationship between inflammation and depression has been demonstrated by an increase in interleukin-6 (IL-6), C-reactive protein (CRP), and tumor necrosis factor-alpha (TNF-α) associated with a higher risk of depression and increased symptoms." (PMID 41333345, 2025). "In addition to elevated levels of IL-6 and TNF-α in depression, these cytokines have been proven to correlate with symptoms of MDD." (PMID 41226404, 2025). "On the other hand, inflammatory mechanisms might have a role in the etiology of depression, with plasma levels of pro-inflammatory cytokines such as TNF, IL-1, and IL-6 predicting its onset." (PMID 39941688, 2025). "Fluoxetine, on the other hand, mitigates cardio-cerebral injury in individuals with myocardial infarction and comorbid depression by suppressing the TNF-α/TNFR/NF-κB pathway in macrophages, while also lowering pro-inflammatory cytokines such as IL - 17 and IFN-γ." (PMID 41000397, 2025). "Furthermore, an immune-related model of depression by intracerebroventricular injection of the tumor necrosis factor (TNF)-like weak inducer of apoptosis (TWEAK) significantly decreased AQP4 protein expression and increased anhedonic behaviour." (PMID 40650814, 2025). "Inhibition of BDNF by TNF-α may contribute to the pathophysiology of depression, as reduced levels of BDNF are commonly observed in depressed individuals." (PMID 40305200, 2025). "Our findings indicate that acupuncture reduces TNF-α and IL-1β levels in the brain tissue of depression animals; it may be due to the fact that acupuncture can regulate inflammatory cell signaling pathways." (PMID 41244868, 2025). "More recently, a survey on the immune profile of people at the first episode of major depression documented a significant activation of immune circuit Th1 compared to the control group, with an increase in inflammatory cytokines such as TNF and IL-6 and also several chemokines." (PMID 40141399, 2025).
depression (continued). "Available research demonstrates that schizophrenia and depression both have shown increased rates of cytokines, including IL-1β, IL-6, and TNF-α, which indicate systemic inflammation followed by cognitive impairment, treatment unresponsiveness, and disturbances in mood." (PMID 40416228, 2025). "In a zebrafish model of T2DM with depression, after 30 days of intervention with pasteurized A. muciniphila, pro-inflammatory cytokine (IL-6, TNF-α, IFN-γ) levels significantly decreased, and anti-inflammatory IL-4 expression increased, resulting in the direct inhibition of neuroinflammation." (PMID 41017972, 2025). "Patients with depression often exhibit increased levels of interleukin-6 (IL-6), IL-1β, IL-10, tumour necrosis factor-α (TNF-α), CRP, and transforming growth factor-β (TGF-β), many of which are produced in response to cellular stress through inflammasome activation." (PMID 41226736, 2025). "Chronic inflammatory states, driven by depression, may lead to increased production of pro-inflammatory cytokines, such as interleukin-6 and tumor necrosis factor-alpha, which are known to damage retinal microvasculature." (PMID 40290656, 2025). "Chronic inflammation has been shown to play a central role in the pathogenesis of various psychiatric disorders, particularly in the development of depression and anxiety, with inflammatory mediators (such as IL-6 and TNF-α) playing a crucial role in their onset and progression." (PMID 41144483, 2025). "Notably, microbiome transplantation in depression models and probiotic interventions in Parkinson’s disease have been shown to reduce pro-inflammatory cytokines (e.g., IL-1β, TNF-α) and normalize microglial activity." (PMID 40371088, 2025). "In a state of depression, circulating levels of TNF-α are significantly elevated." (PMID 41000397, 2025). "The authors found that symptoms experienced by patients with incurable cancer—most often, depression, fatigue, pain, and lack of appetite—were associated with circulating cytokines such as IL-6, interleukin 8, and tumor necrosis factor-alpha, among others." (PMID 39996862, 2025). "Gardnerella vaginalis (GV), an opportunistic pathogen in the vagina, causes vaginitis-, osteoporosis-, and depression-like symptoms through the activation of receptor activator of nuclear factor κB (RANK)/RANK ligand (RANKL)- and TNF/TNF receptor (TNFR)-mediated NF-κB signaling." (PMID 40284791, 2025). "Therefore, we focused on the cytokine TNFα that is prevalent in depression (and inflammation) and described changes under different levels of TNFα concentration." (PMID 40352929, 2025). "Overall, the findings of these studies suggest that a range of cytokines, including IL-6, IL-10, TNF-α, and IL-8, may be involved in the pathophysiology of depression and that further research is needed to understand their roles fully." (PMID 40821647, 2025). "Elevated levels of cytokines such as TNF-α, IL-1β, and IL-6 may exacerbate neuroinflammatory responses, with their concentrations positively correlating with the severity of depression." (PMID 40427467, 2025). "The activation of NLRP3 inflammasome promotes the secretion of Caspase-1, which secretes downstream cytokines, NF-κB, TNFα, and other pro-inflammatory cytokines, and then induces apoptosis, which NLRP3 cascade has been implicated CNS disorders such as depression." (PMID 40308754, 2025). "In addition, it has been reported that chronic pain can autonomously contribute to the pathogenesis of depression by increasing the level/expression of proinflammatory cytokines such as IL-1β, IL-6, and tumor necrosis factor α (TNF-α)." (PMID 40225229, 2025). "However, it is known that in the general population and in PLWH, markers of inflammation or immune activation (such as TNFα, CRP, IL-6) are closely associated to both depression and sleep quality." (PMID 40313235, 2025).
depression (continued). "It has been mentioned in many studies related to the pathogenesis of depression that the activation of microglial in the prefrontal cortex or hippocampus and the release of pro-inflammatory factors such as IL-1β, TNF-α and IL-6 in depressed animals with stress models." (PMID 40336842, 2025). "One hypothesis suggests that gut dysbiosis may contribute to enhanced cytokines release (e.g., IL-1β, IL-6, TNF-α), resulting in a higher activation of the HPA axis and enhancing the risk of developing symptoms of anxiety and depression in IBD." (PMID 39870972, 2025). "However, it is known that dopamine and TNFα levels also play important roles in the occurrence and development of depression." (PMID 40313235, 2025). "Similar findings have been reported in previous studies showing that depression in chronic HBV-infected patients may be associated with immune dysregulation and increased inflammatory cytokines, such as IL-6, IL-8, TNF-α, and TGF-β." (PMID 41239311, 2025). "The findings indicated that the isolated mice displayed clear signs of anxiety and depression-like behaviors, along with increased levels of various cytokines (IL-1β, IL-6, and TNF-α) in the hippocampus and decreased levels of Sirt1, accompanied by elevated NF-κB p65 expression." (PMID 41317200, 2025). "In patients with IBD comorbid with depression, microglia are often in the M1 state, leading to the excessive release of pro‐inflammatory factors such as IL‐1β and tumor necrosis factor α, which further exacerbate central nervous system inflammation and trigger depressive symptoms." (PMID 40823702, 2025). "Furthermore, limonene improved depression in maternally separated mice and reduced neuroinflammation by lowering hippocampal nitrite levels and the expression of IL-1β and TNF-α." (PMID 40443223, 2025). "Similarly, increased concentrations of IL-1β, IL-6, and TNF-α have been reported in older adults with depression and across different depressive subtypes." (PMID 41333345, 2025). "Second, this study focused exclusively on IL-1β, IL-6, and TNF-α as inflammatory biomarkers associated with depression and did not examine the effectiveness of MBTs on other inflammatory markers." (PMID 41194929, 2025). "Moreover, several pro-inflammatory cytokines that play an essential role in depression, such as TNF-α, IL-1β, and IL-6, are suppressed by ghrelin." (PMID 41375608, 2025). "This dysfunction facilitates translocation of LPS into systemic circulation, where it activates peripheral immune cells and stimulates TNF-α secretion.Animal studies further demonstrate that LPS administration induces elevated serum TNF-α levels and depression-like behaviors in mice." (PMID 41000397, 2025). "Analyzing the immunologic changes that accompany depressive disorder, one meta-analysis of 24 studies on clinical patients reports significantly higher concentrations of the pro-inflammatory cytokines TNF-α and IL-6 in depressed patients compared with control ones." (PMID 40333139, 2025). "Canonical pro-inflammatory cytokines, such as CRP, IL-1β, IL-6, and TNF-α, influence the central nervous system (CNS) function and contribute to changes in mood, social behavior, emotion regulation, and the onset and prognosis of depressive disorders." (PMID 41333345, 2025). "Cytokines TNF-α and IL1β also impact the pathogenesis of weakness and pain, and as immune mediators, they indirectly affect the pathophysiological mechanism of depressive syndrome." (PMID 40699818, 2025). "TNF-α could be involved in the pathophysiological process of depression, through mediating astrocytes activation by binding to TNFR1." (PMID 38710713, 2024). "Chronic exposure to stress, including social defeat and immobilization, triggers the release of adrenal hormones like noradrenaline, adrenaline, and glucocorticoids, as well as proinflammatory cytokines like TNF-α and IL-6, leading to depression and anxiety (DA)." (PMID 39519543, 2024).